IL6 (interleukin 6)
Diseases named in the same sentence as IL6 in open-access papers (continued):
Sharing a sentence is not in itself a finding about the gene and the disease.
Obesity (continued). "Obesity is usually associated with overload of proinflammatory cytokines including IL-6, TNF-α, and MCP-1, MMPs and fatty acid binding protein produced by visceral fat, macrophages, and adipocytes." (PMID 24967393, 2014). "For the first time, we also showed that dietary fatty acids modulate the relationship between IL-6 polymorphisms and measures of obesity and serum lipids in both black and white SA women." (PMID 24962479, 2014). "In humans, higher serum IL-6 levels have been associated with elevated likelihood of impaired glucose tolerance, diabetes mellitus, high blood pressure, and especially obesity." (PMID 25548896, 2014). "With IL-6 being expressed by both adipocytes and the stromovascular matrix of visceral WAT, IL-6 is an additional adipokine implicated in the genesis of obesity and insulin resistance." (PMID 25309775, 2014). "Randomized controlled trials are required to examine the effects of specific dietary fatty acids on obesity risk and serum lipids in individuals with a specific IL-6 (or other inflammatory cytokine) genotype." (PMID 24962479, 2014). "This study investigated interactions between dietary fat intake and IL-6 polymorphisms on obesity and serum lipids in black and white South African (SA) women." (PMID 24962479, 2014). "Anyway, the role of IL-6 in metabolic changes associated with obesity is still unclear, despite the anti-inflammatory effect suggested for IL-6 in a recent study." (PMID 24009719, 2013). "Obesity, exercise and diabetes are associated with elevated plasma IL6 concentrations while cerebrospinal fluid (CSF) IL6 levels remain unchanged." (PMID 24015235, 2013). "They used cytokine antibody array to show that BMJ diet supplement reduced plasma levels of some important pro-inflammatory cytokines implicated in obesity-associated adipose tissue inflammation, such as IL-6, TNF-α and MCP-1 in mice with HFD." (PMID 24358329, 2013). "For instance, elevated levels of IL6 in subjects with obesity and diabetes showed an association between insulin resistance and IL6." (PMID 23379763, 2013). "The brief elevation of IL-6, a cytokine upregulated in obesity and closely associated with systemic endothelial dysfunction, in the adipose tissue after five days suggests the significant acute inflammation after that exposure." (PMID 23951156, 2013). "Studies investigating associations between TNFA and IL-6 single nucleotide polymorphisms and obesity and serum lipids." (PMID 23698162, 2013). "Circulatory TNFα and IL-6 are believed to be the pivotal cytokines involved in obesity-associated hepatic inflammation." (PMID 24379011, 2013). "There is growing scientific evidence reporting associations between DNA sequence variants within the IL-6 gene and increased risk of obesity and dyslipidemia." (PMID 23698162, 2013). "Diet–gene interactions between TNFA and IL-6 single nucleotide polymorphisms and dietary fat intake on obesity and serum lipids." (PMID 23698162, 2013). "Obesity has been shown to cause an increase in plasma concentrations of a number of proinflammatory markers (e.g., IL-6, TNF-α) that are expressed and released by adipocytes." (PMID 24453416, 2013). "This review focuses on interactions between single nucleotide polymorphisms (SNPs) in the inflammatory genes TNFA and IL-6, and dietary fatty acids, and their relationship with obesity and serum lipid levels as proof-of-principle examples." (PMID 23698162, 2013). "Obesity is a low-grade inflammatory state that associates with increased secretion of several proinflammatory cytokines, such as tumor necrosis factor-α and interleukin-6, which stimulate CRP production." (PMID 24634792, 2013). "IL6 rs1880242 has been significantly associated with decreased risk of obstructive sleep apnea syndrome; obesity is a strong risk factor for this syndrome." (PMID 23762340, 2013).
Obesity (continued). "Mice deficient in IL-6 (IL6−/−) develop mature onset obesity and have disturbed carbohydrate and lipid metabolism that is partly reversed by IL-6 replacement." (PMID 23984434, 2013). "In contrast, IL-6 deficient mice show mature-onset obesity and hepatic inflammation, and IL-6 administration reverses insulin resistance." (PMID 23781214, 2013). "Obesity and type 2 diabetes are associated with chronically elevated systemic levels of IL-6, a pro-inflammatory cytokine with a role in skeletal muscle metabolism that signals through the IL-6 receptor (IL-6Rα)." (PMID 22761857, 2012). "Specifically, dysregulation of cytokines such as TNF-α and interleukin-6 (IL-6) and adipokines such as lectin and adiponectin contribute to the low-grade inflammation that is a hallmark of obesity." (PMID 22829853, 2012). "The chronic inflammatory response caused by obesity and enhanced production of IL-6 and TNF-α ma also increase the risk not only of HCC but of other cancers." (PMID 22470194, 2012). "Noteworthy is that leptin deficient mice exhibit hyperplasia partly due to increased concentrations of other obesity-associated endocrine and mitogenic factors such as insulin and IL-6." (PMID 23216800, 2012). "Attenuated PKA-mediated signaling to HSL, loss of PLIN1a and increased secretion of IL-6 were also observed in adipose tissue explants of CAV1+/+ mice with diet-induced obesity." (PMID 23049990, 2012). "The TNF-α, IL-6 and AdipoQ polymorphisms were selected considering the participation of these cytokines in underlying mechanisms of obesity-related metabolic disturbances, such as inflammation and insulin resistance." (PMID 23176569, 2012). "Obesity-promoted HCC development was dependent on the production of the tumor-promoting cytokines IL-6 and TNF-α, which cause hepatic inflammation and activation of the oncogenic transcription factor STAT3." (PMID 22470194, 2012). "Biological evidence indicated that high levels of interleukin 6 and tumor necrosis factor, which are associated with obesity, turned healthy cells into malignant ones through chronic low-grade inflammation of the liver." (PMID 23028553, 2012). "In both mice and humans, high fat diet and obesity are associated with increased adipose tissue macrophages, which are responsible for secreting most of the IL-6 and TNF-α produced by adipose tissue." (PMID 22935594, 2012). "We identified the increase in reactive oxygen species in combination with obesity-associated low adiponectin and high glucose and interleukin-6 as cause of the decrease in IRAK3 in THP-1 cells in vitro." (PMID 22272346, 2012). "IL-6 is markedly produced during the post-exercise period when insulin action is enhanced, but IL-6 is also associated with obesity and reduced insulin action." (PMID 23136874, 2012). "Several studies associate obesity with chronic inflammation since blood markers, such as the proinflammatory cytokine interleukin 6 (IL-6) and tumour necrosis factor α (TNFα), are increased in these patients." (PMID 22144986, 2011). "The development of obesity has been linked to an inflammatory process, and the role of adipose tissue in the secretion of pro-inflammatory molecules such as IL-6 or TNFalpha has now been largely confirmed." (PMID 20148136, 2010). "As in obesity, aging is frequently associated with increased fat tissue and circulating pro-inflammatory cytokines, including TNFα and IL-6." (PMID 20701600, 2010). "On the other hand, IL-1 receptor antagonist-deficient mice (IL-1Ra−/− mice) are resistant to monosodium glutamate (MSG)-induced obesity while IL-6-deficient mice develop a late onset-obesity." (PMID 20376352, 2010). "Previous studies reported elevated levels of plasma TNF- α and IL-6 in obese rodent models and in humans, which are implicated in the development of obesity induced insulin resistance and diabetes." (PMID 21083914, 2010).
Obesity (continued). "Their data demonstrated that the occurrence of C allele of IL-6-174G>C gene polymorphism in people with excessive body weight was accompanied by increased risk of developing obesity-related metabolic disorders, especially insulin resistance." (PMID 19804633, 2009). "Data on C-174G polymorphism of IL-6 suggest that it affects the IL-6 transcription rate and plays a role in the development of obesity and insulin sensitivity." (PMID 19804633, 2009). "Adipocyte enlargement, as observed in obesity, is associated with dysfunctional fat cells which over-express and secrete excessive amounts of leptin, IL-6, TNFα, resistin, MCP-1 and FFA while under secreting adiponectin." (PMID 19656356, 2009). "APOE alleles and genetic variants of IL-6 have also been established to be factors of susceptibility to obesity." (PMID 19804633, 2009). "In mice, IL-6 deficiency has been reported to induce a mature-onset obesity that appears after 6 months of life." (PMID 19936233, 2009). "Initial evidence for a functional interplay was created by increased serum levels of IL6 in obesity in which IL6 was found to be associated with insulin resistance." (PMID 19087258, 2008). "Cardiovascular diseases, diabetes, obesity, cancer and other pathologies are associated with increased production of thromboxane A2, leukotriene B4, Il-1β, IL-6 and TNF." (PMID 17313679, 2007). "However, other studies have reported no obvious age-dependent metabolic changes in mutant mice sharing either the IL-6−/− or Stat3Δhep alleles identical to those in mice that do develop mature-onset obesity." (PMID 41362820, 2026). "Likewise, obesity is associated with altered expression and functions of additional cytokines, including interleukin-6 (IL-6), interleukin-1 (IL-1)." (PMID 40406485, 2025). "Furthermore, obesity is characterized as a pro-inflammatory state, associated with elevated levels of pro-inflammatory cytokines, including tumor necrosis factor and interleukin-6." (PMID 41016748, 2025). "Obesity is associated with the presence of prothrombotic factors (e.g., fibrinogen, homocysteine), inflammatory markers (e.g., interleukin-6 (IL-6), tumor necrosis factor-alpha (TNF-α), C-reactive protein (CRP)), and adipocytokines (e.g., leptin, adiponectin))." (PMID 39857920, 2025). "Conversely, obesity is associated with increased IL-6, TNF-α, and IL-1β levels, creating a pro-inflammatory state that could contribute to depressive symptoms." (PMID 41375608, 2025). "Furthermore, KRAS mutations combined with lifestyle factors, such as obesity, exacerbate NK cell suppression by increasing interleukin-6 (IL-6) production and decreasing interferon-gamma (IFN-γ) levels, impairing NK cell-mediated immune responses." (PMID 39859231, 2025). "Moreover, obesity-induced adipose tissue inflammation, characterized by elevated macrophage infiltration and pro-inflammatory cytokine production (e.g., TNF-α, IL-6), plays a crucial role in the pathogenesis of obesity-associated metabolic disorders." (PMID 40004080, 2025). "Moreover, other studies emphasised that elevated CRP and IL-6 levels are associated with an increased risk of HF in individuals with obesity and metabolic syndrome." (PMID 40814000, 2025). "Obesity is associated with a low-grade chronic inflammatory state, characterised by the elevation of pro-inflammatory cytokines, including but not limited to interleukin-6 (IL-6) and tumor necrosis factor-alpha (TNFα)." (PMID 40564637, 2025). "On a similar note, a state of obesity by itself is a risk factor of periodontal destruction and it increases the release of adipokines (such as leptin and resistin) and destructive inflammatory cytokines such as IL-6." (PMID 41396032, 2025). "We did not collect data on inflammatory biomarkers such as C Reactive Protein, IL-6, or adipokines, despite increasing evidence that chronic low-grade inflammation plays a key role in the metabolic and cardiovascular risks associated with obesity." (PMID 41010615, 2025).
Obesity (continued). "IL-6 is involved in the regulation of inflammation and the maintenance of energy homeostasis, and its dysregulation is associated with the progression from acute to chronic inflammatory states, particularly in the contexts of obesity and insulin resistance." (PMID 40283443, 2025). "Obesity, now classified as a low-grade chronic inflammatory state, is linked to elevated circulating levels of pro-inflammatory cytokines including interleukin-6 (IL-6), tumor necrosis factor-alpha (TNF-α), and leptin, which can adversely affect periodontal tissues and exacerbate disease severity." (PMID 40922027, 2025). "A recent prospective observational study from the Nordic Rheumatic Diseases Strategy Trials and Registries showed that obesity was associated to a reduced effectiveness of treatments for RA, including biologic DMARDs such as selective T‐cell co‐stimulation modulators and IL‐6 inhibitors." (PMID 39760506, 2025). "Acutely, an increase in IL-6 has been linked with a reduction in obesity and glucose intolerance." (PMID 41155560, 2025). "Interestingly, leptin and IL-6 were the only factors associated with Cohaesibacteraceae and Rhodospirillaceae families, highlighting additional microbial signatures for obesity-enhanced psoriasis." (PMID 40869018, 2025). "While obesity is associated with reduced levels of adiponectin and increased content of inflammatory macrophages in adipose tissue, in some immunoinflammatory diseases such as RA, increased adiponectin levels are associated with a concomitant increase of IL‐6." (PMID 39760506, 2025). "The IL‐6‐dependent accumulation of Th17 lymphocytes in WAT may also support the propagation of obesity‐associated pro‐inflammatory responses." (PMID 39763022, 2025). "In murine models of tissue-specific gene knockout, myeloid Il6 deficiency worsens inflammation and metabolic outcomes in obesity; adipose Il6 deficiency dampens inflammation and improves metabolic outcomes; and muscle Il6 deficiency has no influence on metabolic outcomes." (PMID 40553147, 2025). "Men with risk factors (obesity, sedentary life, smoking) often show higher IL-6/CRP levels than comparably affected women, while higher CRP concentrations in premenopausal women appear to result from their greater accumulation of subcutaneous fat compared to men." (PMID 41425557, 2025). "In PCOS, IL-6 is linked to metabolic disturbances, including insulin resistance and obesity." (PMID 40385768, 2025). "In obesity, chronically elevated IL-6 levels may exert beneficial or pathogenic effects on energy metabolism across multiple organs, including the liver, pancreas, and adipose tissue." (PMID 40244195, 2025). "Activated microglia and astrocytes, responding to obesity-associated inflammation, adopt prolonged pro-inflammatory states, releasing interleukin 1β (IL-1β), IL-6, TNF-α, reactive oxygen species (ROS), and proteases such as matrix metalloproteinases (MMPs) and cathepsins." (PMID 41155642, 2025). "Moreover, the pathogenesis of meta-inflammation is closely linked to the well-characterized phenomenon of elevated IL-6 and its receptor expression in the adipose tissue during obesity." (PMID 41199597, 2025). "In fact, obesity, itself indicating a chronic state of low-level inflammation, has been associated with generally elevated levels of pro-inflammatory cytokines, including IL-6, TNF, as well as iNOS detectable in serum." (PMID 40508229, 2025). "A recent meta-analysis suggested that the minor alleles of rs1800795 in the IL-6 gene could be associated with a higher risk of obesity." (PMID 39769263, 2024). "This may suggest that elevated CSF IL‐6 associated with obesity/overweight is unrelated with peripheral IL‐6." (PMID 39401137, 2024). "Baring complex biology, our finding that obesity is associated with increased leptin and IL-6 supports the observed effect of patient BMI on cancer cell invasiveness and migration, because these two adipokines stimulate breast cancer migration and invasiveness." (PMID 39408921, 2024).
Obesity (continued). "Moreover, the IL-6-174G>C polymorphism in the IL-6 promoter region significantly increases the risk of obesity." (PMID 38397196, 2024). "A recent meta-analysis indicated that the minor alleles of rs1800795 in the IL-6 gene may be linked to an increased risk of obesity." (PMID 39769263, 2024). "Excessive IL-6 is associated with metabolic impairment in obesity: when IL-6 is released in excess, it may promote adipose tissue inflammation, insulin resistance and diabetes." (PMID 38474057, 2024). "Nevertheless, IL-6 appears as a powerful inducer of fat loss, and hence, regulation of adipose tissue IL-6 synthesis may emerge as a novel therapeutic target in obesity management." (PMID 38474057, 2024). "In line with this notion, mutations in PCa that activate PI3K (such as prostate-specific Pten loss) prime or promote obesity-driven PCa aggressiveness in conjunction with other signalling pathways, such as loss of Ptpn1, IL6/pSTAT3 signalling activation or Pml co-deletion." (PMID 38969865, 2024). "Obesity is associated with increased production of reactive oxygen species (ROS) and inflammatory adipokines such as resistin, tumor necrosis factor alpha (TNFα), and interleukin 6 (IL-6), as well as a reduction in anti-inflammatory adipokines (adiponectin)." (PMID 39334752, 2024). "According to previous study, obesity increases the crosstalk between chondrocytes and synovial fibroblasts by elevating levels of the pro-inflammatory adipokine leptin, which causes OA patients to produce more IL-6." (PMID 37608129, 2024). "Moreover, IL6 has been implicated in regulating insulin resistance and obesity, as genetic deletion of IL6 in mice leads to obesity and glucose intolerance, and elevated serum IL6 levels are associated with insulin resistance in patients with T2D and obesity." (PMID 38667300, 2024). "IL-6 is associated with proinflammatory effects in obesity that can induce insulin resistance." (PMID 38822155, 2024). "Increased white-adipose-tissue (WAT) content, which constitutes the hallmark of obesity, leads to enhanced secretion of adipokines, including leptin, resistin, interleukin 6 (IL-6), tumor necrosis factor-alpha (TNF-α), visfatin, vaspin, and retinol-binding protein 4 (RBP-4)." (PMID 38794651, 2024). "The pathology of obesity-related arrhythmias is associated with abnormal accumulation of lipids (lipotoxicity), which induces an increase in proinflammatory cytokines, including IL-6, elevating the risk of adverse ventricular electrical remodeling." (PMID 39063055, 2024). "Obesity is associated with an increased circulating levels of inflammatory cytokines such as interleukin-6 (IL-6) and tumour necrosis factor- alpha (TNF- α) that may trigger an increase in the number of cells that have tumour-forming potential." (PMID 38709714, 2024). "Compare people with significant differences in obesity degree, a total of 25 miRNAs have been identified as targeting three upregulated adipogenesis-associated inflammatory genes, namely interleukin-6 (IL-6), tumour necrosis factor-alpha (TNF-α), and interleukin-1 beta (IL-1β)." (PMID 38982993, 2024). "Obesity could trigger immune-inflammatory pathways, causing adipose tissue to release inflammatory cytokines like tumor necrosis factor-α and interleukin-6, which can impair brain function and precipitate depressive symptoms." (PMID 39957754, 2024). "Obesity is a chronic inflammatory disorder, associated with adipocyte hypertrophy and secretion of pro-inflammatory cytokines, such as interleukin (IL)-6, IL-1, IL-8, and tumor necrosis factor (TNF)-α, as well as adipokines such as leptin, adipsin, resistin, and visfatin by adipose tissue." (PMID 38864906, 2024). "It is worth noting that obesity, even in women who complete a normal pregnancy, seems to be associated with an unfavorable gene profile of IL-6 with an increased frequency of the G allele, which is found in women who experience problems in pregnancy, as we found in our study." (PMID 38893732, 2024).